ITGA7 (integrin subunit alpha 7)
Description:
Integrin alpha-7/beta-1 is the primary laminin receptor on skeletal myoblasts and adult myofibers. During myogenic differentiation, it may induce changes in the shape and mobility of myoblasts, and facilitate their localization at laminin-rich sites of secondary fiber formation. It is involved in the maintenance of the myofibers cytoarchitecture as well as for their anchorage, viability and functional integrity. Isoform Alpha-7X2B and isoform Alpha-7X1B promote myoblast migration on laminin 1 and laminin 2/4, but isoform Alpha-7X1B is less active on laminin 1 (In vitro). Acts as a Schwann cell receptor for laminin-2. Acts as a receptor of COMP and mediates its effect on vascular smooth muscle cells (VSMCs) maturation (By similarity). Required to promote contractile phenotype acquisition in differentiated airway smooth muscle (ASM) cells.
Tractability: Antibody: its Gene Ontology location is reachable by antibodies, with high confidence; UniProt predicts a signal peptide or a membrane-spanning region; the Human Protein Atlas places it where antibodies can reach. PROTAC: ubiquitination databases record sites on it.
Gene: Protein-coding gene on chromosome 12 (55,684,568 to 55,716,404, reverse strand). Ensembl gene ENSG00000135424.
Subcellular location: Membrane
Subcellular location (Human Protein Atlas): Plasma membrane; Nuclear speckles; Vesicles
Pathways (Reactome):
Extracellular matrix organization: ECM proteoglycans; Integrin cell surface interactions; Laminin interactions
Gene Ontology:
Molecular function: protein binding; signaling receptor activity
Biological process: endodermal cell differentiation; heterotypic cell-cell adhesion; cell-cell adhesion; cell-matrix adhesion; integrin-mediated signaling pathway; leukocyte migration; muscle organ development; cell adhesion
Cellular component: cell surface; integrin complex; plasma membrane; membrane
Genetic constraint (gnomAD): Loss-of-function variants: 83 observed, 135.02 expected, observed/expected ratio (o/e) 0.61, 90% interval 0.51 to 0.74. The upper end of that interval is the gene's LOEUF score, 0.74, which puts it in group 3 of 6, group 1 being the genes least tolerant of losing a copy. Missense variants: 1,395 observed, 1,520.3 expected, observed/expected ratio (o/e) 0.92, 90% interval 0.88 to 0.96. Synonymous variants: 548 observed, 619.43 expected, observed/expected ratio (o/e) 0.88, 90% interval 0.82 to 0.95.
Homologues: Orthologues: chimpanzee ITGA7 (99% identical), macaque ITGA7 (95% identical), dog ITGA7 (92% identical), guinea pig ITGA7 (91% identical), rabbit ITGA7 (90% identical), pig ITGA7 (89% identical), mouse Itga7 (88% identical), rat Itga7 (85% identical), tropical clawed frog ITGA7 (58% identical), Drosophila melanogaster mew (28% identical), Caenorhabditis elegans ina-1 (26% identical), Drosophila melanogaster if (23% identical), and 4 more. Paralogues in human: ITGA6 (45% identical), ITGA3 (34% identical), ITGAV (25% identical), ITGA8 (25% identical), ITGA5 (25% identical), ITGA2B (23% identical), ITGA4 (22% identical), ITGA9 (22% identical), ITGA2 (21% identical), ITGA1 (21% identical), ITGA10 (21% identical), ITGA11 (21% identical), and 5 more.
Diseases named in the same sentence as ITGA7 in open-access papers:
ITGA7 is named in the same sentence as 83 diseases in open-access papers, as found by Europe PMC text mining. Sharing a sentence is not in itself a finding about the gene and the disease. The quoted sentences say what the papers report.
colorectal cancer (15 papers, 2019 to 2025). A primary or metastatic malignant neoplasm that affects the colon or rectum. "The circular RNA circITGA7, formed by exon 4, regulates the Ras pathway and up-regulates the transcriptional repression of its host gene, ITGA7, thereby inhibiting the growth and metastasis of colorectal cancer." (PMID 38275418, 2024). "A study revealed that circITGA7 and its linear host gene ITGA7 are both significantly downregulated in colorectal cancer (CRC) tissues and cell lines." (PMID 35965538, 2022). "FOXC1 is overexpressed and promotes colorectal cancer metastasis by activating the expression of ITGA7 and FGFR4." (PMID 34957298, 2021). "CircITGA7 inhibited colorectal cancer growth and metastasis by modulating the Ras pathway and upregulating the transcription of its host gene ITGA7." (PMID 33407501, 2021). "On the other hand, RREB1 inhibition by circITGA7 will increase the expression of ITGA7 to inhibit colorectal cancer growth." (PMID 32210733, 2020). "For example, circRNA ITGA7 regulated colorectal cancer proliferation by sponging miR-3187-3p to elevate ASXL1 expression." (PMID 32714095, 2020). "CircITGA7 has been shown to inhibit the proliferation and metastasis of colorectal cancer cells by inhibiting the Ras signaling pathway and promoting the transcription of the host gene ITGA7." (PMID 32196072, 2020). "Interestingly, HSPB6 and ITGA7 were downregulated in colorectal cancer, suggesting potential transcriptional positive regulation." (PMID 37241227, 2023). "Researchers also find that circITGA7 can inhibit the metastasis and proliferation of colorectal cancer cells by inhibiting the pathway of Ras signal and promoting the transcription of its downstream target gene ITGA7, thus playing its antitumor roles in colorectal cancer." (PMID 33884267, 2021). "Researchers indicated a tumour suppressor role for circITGA7 and ITGA7 in colorectal cancer and revealed that circITGA7 inhibits proliferation and metastasis of colorectal cancer cells by suppressing the Ras signalling pathway and promoting the transcription of ITGA7." (PMID 30626395, 2019). "Circular RNAs have been reported to be widely involved in cancer cell tumorigenesis and drug resistance; here, the aim of this study was to investigate whether circRNA Integrin Subunit Alpha 7 (ITGA7) (circ_ITGA7) was associated with the tumor growth and radiosensitivity of colorectal cancer (CRC)." (PMID 36694626, 2023). "Promoter hypermethylation has been shown to suppress ITGA7 expression, leading to activation of the PI3K/AKT/NF-κB pathway and enhanced proliferation and migration in colorectal cancer." (PMID 41235257, 2025).
breast carcinoma (9 papers, 2020 to 2025). "Our next aim was to test in a further cohort of breast cancers whether levels of ITGA7 protein expression were differentially associated with histopathological features of tumours, or with cancer outcomes specifically after chemotherapy." (PMID 34253873, 2021). "Next, we aimed to test directly whether expression levels of ITGA7 are associated with differential sensitivity of breast cancer cells to cytotoxic chemotherapy." (PMID 34253873, 2021). "Traditionally recognized as a tumor suppressor, ITGA7 is significantly downregulated in breast cancer stem cells (BCSCs)-key contributors to therapy resistance and adverse clinical outcomes." (PMID 41235257, 2025). "ITGA7 serves as a tumor suppressor gene in breast cancer (BC) and modulates BC invasion and migration." (PMID 37963970, 2023). "Here, we identify the consistent transcriptome of primary BCSCs shared across breast cancer subtypes, and we examine the clinical relevance of ITGA7, one of the genes differentially expressed in BCSCs." (PMID 34253873, 2021). "ITGA7 expression was examined in breast cancers using immunohistochemistry (n = 305), and its functional role was tested using siRNA in breast cancer cells." (PMID 34253873, 2021). "We concluded that ITGA7 was a strong candidate mediator of chemotherapy response in breast cancer, and therefore worthy of direct experimental testing." (PMID 34253873, 2021). "The ITGA7 variant was identified in five assayed breast cancer cases, but they were not related to the original variant-carrying cousin pair, nor to each other." (PMID 38136396, 2023). "ITGA7 also plays an important tumorigenic function and acts as a suppress gene in breast cancer." (PMID 36059637, 2022). "Next, we assessed whether ITGA7 expression impacted on cancer outcomes using publicly-available transcriptome data for primary breast cancer samples." (PMID 34253873, 2021). "ITGA7 upregulation promotes the proliferation and invasion of breast cancer cells." (PMID 34503278, 2021). "ITGA7 was found to be significantly downregulated in BCSCs, and low expression significantly correlated with reduced survival in patients treated with chemotherapy, and with chemoresistance in breast cancer cells in vitro." (PMID 34253873, 2021). "Using the profile, we have identified ITGA7 as a mediator of the stem-like property of chemoresistance, and define ITGA7 as a predictive marker for chemoresponse in breast cancer, thereby highlighting integrins for future study in order to consider novel chemo-sensitisation strategies." (PMID 34253873, 2021). "Using the METABRIC dataset, we tested whether ITGA7 expression levels correlated with disease-free survival in a cohort of breast cancer cases (n = 1903), or in the same cases separating them into those annotated as receiving chemotherapy (n = 396) and those not so annotated (n = 1507)." (PMID 34253873, 2021). "ITGA7, which acts as a receptor for a number of laminins, has also recently been implicated in chemoresponse, although not in the context of breast cancer." (PMID 32734521, 2020). "We transfected the breast cancer cell line MCF7 with siRNAs targeting ITGA7, or with control non-targeting siRNAs, and assessed ITGA7 expression using this antibody by Western blot and immunofluorescence." (PMID 34253873, 2021).
glioblastoma (8 papers, 2009 to 2024). The most malignant astrocytic tumor (WHO grade IV). "Although the expression of ITGA7 in glioblastomas correlates to poor prognosis, the clinical significance of ITGA7 expression is controversial in other malignancies, and its role and expression in AML have not yet been characterized." (PMID 32033262, 2020). "High ITGA7 surface expression has been negatively correlated with glioblastoma patient survival, and targeting ITGA7 by RNAi has been shown to lead to a significant reduction of tumor cell invasion in vitro." (PMID 29721158, 2018). "Recently, increasing evidences have demonstrated ITGA7 as a tumor suppressor gene in many human malignant neoplasms, including prostate cancer, liver cancer, glioblastoma multiforme and leiomyosarcoma." (PMID 25887589, 2015). "Moreover, the evaluation of ITGA7 microarray data of glioblastoma patients from the Cancer Genome Atlas (TCGA) shows that the higher expression of ITGA7 correlates with a poor prognosis." (PMID 37686355, 2023). "Various research groups have analyzed functional markers in BTSC to narrow therapeutic approaches: among them a recent report identified integrin α-7 (ITGA7) as a key regulator in GSCs proliferation, and demonstrated its involvement in glioblastoma growth rate and invasiveness." (PMID 37686355, 2023). "However, ITGA7 was highly expressed in glioblastoma multiforme (GBM) tissues in comparison with adjacent normal tissues." (PMID 34504842, 2021).
muscular dystrophy (8 papers, 2012 to 2023). Muscular dystrophy (MD) refers to a group of more than 30 genetic diseases characterized by progressive weakness and degeneration of the skeletal muscles that control movement. "The “canonical” receptors, Dag1 and Itga7, are highly expressed and, when mutated, lead to congenital muscular dystrophies." (PMID 23109907, 2012). "Muscular dystrophy was observed in patients with ITGA5 or ITGA7 mutations." (PMID 31623094, 2019). "The integrin α7β1 is a receptor for laminins, with deletion of Itga7 in mice leading to muscular dystrophy-like phenotypes due to defective adhesion and signaling pathways in skeletal muscle cells." (PMID 33031376, 2020). "Yet the presence of a group of mutated genes linked to myopathies (ITGA7, NRAP, POLM, SCN5A, XIRP2) and muscular dystrophy (ITGA7) raises a question about the involvement of these muscular pathologies in hernia genesis and unsuccessful hernia repairs associated with the current case." (PMID 38021525, 2023). "The relationship between the common variants in LAMA2, DAG1 and ITGA7 that are associated with myopia and the mutations in these same genes causing muscular dystrophy is not clear." (PMID 36737489, 2023).
congenital myopathy (4 papers, 2013 to 2022). "ITGA7 is highly expressed in cardiac, skeletal, and smooth muscle cells, and it has been reported that mutations in ITGA7 can be associated with congenital myopathy and incompressible cardiomyopathy." (PMID 35628462, 2022).
esophageal squamous cell carcinoma (4 papers, 2019 to 2025). Esophageal squamous cell carcinoma (ESCC) is a type of esophageal carcinoma (EC) that can affect any part of the esophagus, but is usually located in the upper or middle third. "For instance, ITGA7 was associated with cancer stemness in esophageal squamous cell carcinoma and correlates with poor prognosis in hepatocellular carcinoma." (PMID 36930369, 2023). "Therefore, ITGA7 represents a potential functional stem cell marker for esophageal squamous cell carcinoma." (PMID 39239559, 2024). "The ITGA7 (+) cells isolated from esophageal squamous cell carcinoma and cells overexpressing ITGA7 exhibit stronger stemness characteristics, including elevated expression of stemness-related genes and enhanced abilities in self-renewal, differentiation, and resistance to chemotherapy." (PMID 39239559, 2024). "In esophageal squamous cell carcinoma (OSCC), ITGA7 regulates CSC properties through the activation of FAK-mediated signaling pathways." (PMID 39239559, 2024).
hepatocellular carcinoma (4 papers, 2018 to 2023). A malignant tumor that arises from hepatocytes. "ITGA7 regulates cell proliferation via the PTK2-PI3K-Akt signalling pathway and is negatively associated with clinical outcomes in hepatocellular carcinoma, and via the laminin-integrin α7β1 signalling pathway in mechanical ventilation-induced pulmonary fibrosis." (PMID 34409913, 2021). "ITGA7 is highly expressed in hepatocellular carcinoma cells and knockdown of ITGA7 inhibits proliferation, migration, invasion and EMT of hepatocellular carcinoma cells." (PMID 36267977, 2022). "However, a recent publication, based on tumor tissue derived from hepatocellular carcinoma patients and from an animal model, reports that activated Akt signaling, a typical feature of temsirolimus resistance, may correlate with ITGA7 expression and tumor metastasis." (PMID 29721158, 2018).
cardiomyopathy (3 papers, 2022 to 2025). A disease of the heart muscle or myocardium proper. "Overexpression of ITGA7 promotes cellular regeneration and hypertrophy while reducing cardiomyopathy." (PMID 41468376, 2025). "Recent studies on ITGA7 includes its effect on muscle stem cells polarity, adult-onset cardiomyopathy, and tumor progression, prognosis." (PMID 40758665, 2025).
congenital muscular dystrophy (3 papers, 2017 to 2021). A muscular dystrophy that is characterized by diminished muscle tone (hypotonia), progressive muscle weakness and degeneration (atrophy), abnormally fixed joints, spinal rigidity, and delays in reaching motor milestones such as sitting or standing unassisted. "Itga7 is also required for muscle homeostasis: mutations in Itga7 lead to congenital muscular dystrophy with Itga7 deficiency." (PMID 31391079, 2019). "Mutations in Itga7 result in Itga7-linked congenital muscular dystrophy." (PMID 34842731, 2021).
glioma (3 papers, 2021 to 2022). A benign or malignant brain and spinal cord tumor that arises from glial cells (astrocytes, oligodendrocytes, ependymal cells). "Furthermore, although not correlating to response to irradiation, recent studies have shown that COL1A1, ITGA7, ITGB3, ITGB4, HMMR and IBSP upregulation confer low survival rate to glioma patients." (PMID 34211843, 2021). "In contrast to glioma stem cells, U87 cells showed no overexpression of stem cell markers, such as SOX2, ZEB1, ATXN1, ALCAM, CD9, ITGA7, CD44 and CHI3L1." (PMID 34680293, 2021).
Parkinson disease (3 papers, 2021 to 2022). A progressive degenerative disorder of the central nervous system characterized by loss of dopamine producing neurons in the substantia nigra and the presence of Lewy bodies in the substantia nigra and locus coeruleus. "Given that METH can often lead to pathological changes similar to those seen in Alzheimer’s disease and Parkinson’s disease, the role of ITGA7 and COL6A1 in METH-induced neurotoxicity warrants deeper understanding." (PMID 36204112, 2022). "A study investigated that inhibition of ITGA7 down-regulated the expression of BCL2 and increased the BAX/BCL2 ratio, causing apoptosis of SH-SY5Y cells in Parkinson’s disease mouse models." (PMID 36204112, 2022). "We investigated the potential association between integrin α7 (ITGA7) and alpha-synuclein (α-syn) in a methyl-4-phenyl-1,2,3,6-tetrahydropyridine (MPTP)-induced Parkinson’s disease (PD) mouse model." (PMID 34884422, 2021). "In this study, ITGA7 expression was found to be reduced in the SN of an MPTP-induced Parkinsonism mouse model." (PMID 34884422, 2021). "Herein, we report that ITGA7 expression is reduced in the SN in a 1-methyl-4-phenyl-1,2,3,6-tetrahydropyridine (MPTP)-induced Parkinsonism mouse model." (PMID 34884422, 2021).
cardiac hypertrophy (2 papers, 2016 to 2025). "Further investigation into the roles of miR-34a, miR-351, and miR-490*, alongside validated genes such as HTR2A, SGPP1, ITGA7, and GANC is essential to elucidate their contributions to early-onset cardiac hypertrophy." (PMID 41468376, 2025).
colon adenocarcinoma (2 papers, 2021 to 2026). "Besides, in many other tumors, such as rectum adenocarcinoma, colon adenocarcinoma, and breast invasive carcinoma (BRCA), ITGA7 was also lowly expressed." (PMID 34504842, 2021). "The expression level of ITGA7 was decreased in tumor tissues such as BLCA, BRCA, cervical squamous cell carcinoma and endocervical adenocarcinoma (CESC), colon adenocarcinoma (COAD), LUSC, PRAD, and UCEC." (PMID 41602372, 2026).
Duchenne muscular dystrophy (2 papers, 2018 to 2022). Duchenne muscular dystrophy (DMD) is a neuromuscular disease characterized by rapidly progressive muscle weakness and wasting due to degeneration of skeletal, smooth and cardiac muscle. "Overexpression of ITGA7 prevents loss of force and increases the diaphragm-specific force following contraction-induced injury, supporting the application of ITGA7 as a potential therapeutic for Duchenne muscular dystrophy." (PMID 35628462, 2022). "Based on a mouse model of Duchenne muscular dystrophy, ITGA7 was shown to cross-communicate with the Akt-mTOR-axis, leading to signal amplification and growth promotion." (PMID 29721158, 2018). "Notably, ITGA7, typically concentrated at the muscle–tendon junctions of postnatal muscles, is upregulated throughout the sarcolemma in Duchenne muscular dystrophy." (PMID 35628462, 2022).
liver cancer (2 papers, 2015 to 2020). An epithelial or non-epithelial malignant neoplasm that arises from the liver. "The OS and disease-free survival of patients with liver cancer and lung cancer with high ITGA7 expression are shorter." (PMID 33335550, 2020). "ITGA7 is highly expressed in liver cancer and non-small cell lung cancer." (PMID 33335550, 2020).
melanoma (2 papers, 2024 to 2025). A malignant, usually aggressive tumor composed of atypical, neoplastic melanocytes. "Notably, we identified differentially expressed cell surface markers including MCAM (CD146), CSPG4, and ITGA6/ITGA7, which are well-established melanoma resistance markers." (PMID 41000875, 2025).
papillary thyroid carcinoma (2 papers, 2024 to 2025). "For example, cellular ITGA7 has been found to influence migration, invasion, and epithelial–mesenchymal transition to function as a tumor suppressor gene in BC and papillary thyroid carcinoma cells." (PMID 38339272, 2024).